EPCAM (epithelial cell adhesion molecule)
Diseases named in the same sentence as EPCAM in open-access papers (continued):
Sharing a sentence is not in itself a finding about the gene and the disease.
tumor (continued). "CSCs contained specific biomarkers like EPCAM, which were participated in their effect to escape the immune system, to facilitate tumor growth and to generate colonies." (PMID 35150083, 2022). "Tumor cells expressing EpCAM exhibited an enhanced capacity to initiate cancer formation, as well as other stemness properties (chemo/radioresistance, elevated tumorigenicity, angiogenesis, hypoxia tolerance and metastatic colony formation ability)." (PMID 36369033, 2022). "Epithelial cell adhesion molecule (EpCAM) is abnormally expressed in a variety of human tumor tissues and is involved in tumor genesis." (PMID 36056339, 2022). "Here, the molecules responsible for the cellular adhesion and specific tumor recognition were reported to be EpCAM, N-cadherin and galectin-3, which were present on the cancer cell surface." (PMID 34070233, 2021). "Preclinical studies have demonstrated the feasibility of an EpCAM-specific fluorescence contrast agent for tumor visualization." (PMID 33799475, 2021). "The localization of FF-10832 in tumors was further analyzed using fluorescence-activated cell sorting, in which F4/80 and EpCAM were used as marker antigens for macrophages and tumor cells, respectively." (PMID 33961188, 2021). "The expression patterns in the metastases generally mirrored the expression patterns in the primary tumor, indicating that EpCAM expression is important for metastatic development in epithelial cancers." (PMID 34209658, 2021). "By aspirating only dispensed droplets that contain fluorescent cells for RNA isolation, we obtained promising PCR results detecting even small numbers of EpCAM+ tumor cells with low WBC background signal." (PMID 34829387, 2021). "EpCAM is expressed on circulating tumor and cancer stem cells undergoing EMT and modulates metastases and cancer treatment responses." (PMID 34209658, 2021). "Despite to the low number of patients, the results of this ex vivo study indicate a complete removal of EpCAM positive tumor cells, which has to be validated in a clinical study." (PMID 34715784, 2021). "Several studies have indicated that EpCAM plays critical roles in the migration, proliferation, and differentiation of tumor cells." (PMID 34439276, 2021). "83% of all CD8+ T cells were in direct contact with tumor cells after 7 d of solitomab treatment compared with 24% in EpCAM antibody–treated controls (P < 0.01, Student’s t test)." (PMID 34415995, 2021). "EpCAM-positive tumor cells were detectable in the urine but continuously dropped from 111 to 0, 52 days after the last instillation of the second treatment cycle." (PMID 33837852, 2021). "EpCAM is thought to have a critical function in cancer and to drive malignant properties of tumor cells." (PMID 34943898, 2021). "Epithelial cell adhesion molecule (EpCAM) is widely expressed in PCa, and can differentiate between tumor and stroma cells." (PMID 34834440, 2021). "In coculture with EpCAM positive tumor cells, the capturing efficiency of Ab conjugated hybrid shell–magnetic core NPs was about 95%." (PMID 33898169, 2021). "It mediates the metastasis of tumor cells and brings about poor prognosis for patients by regulating EPCAM and affecting the enrichment of NK cells." (PMID 33535187, 2021). "With enriched blood plasma exosome in microfluidic devices, immunomagnetic beads are employed to capture and measure exosomal tumor markers (such as CA-125, EpCAM, and CD24)." (PMID 34885161, 2021). "Higher-magnification 3D modeling confirmed CMV-specific T cell interactions were far more frequent with EpCAM+/GFP+ tumor cells, but less so with EpCAM−/mCherry+ cells at 11 dpt (P < 0.001, Student’s t test)." (PMID 34415995, 2021). "We proceeded to evaluate the therapeutic activity of mGFP CAR T cells/control T cells, EpCAM CAR T cells, and EpCAM CAR T cells plus hsBCL9CT-24 in NSG mice with subcutaneous xenograft tumor models established with HCT116." (PMID 34790117, 2021).
tumor (continued). "In agreement with their findings, we observed a binding-site barrier on the outside of the spheroids when using tumor cells that overexpress membrane molecules such as EpCAM or HER2, and DARPins against these targets." (PMID 34070171, 2021). "In this study, tumour-derived EVs were first captured by CD63-aptamer-modified microbeads followed by addition of two aptamers targeting the membrane proteins EpCAM and HER2 on EVs." (PMID 34855021, 2021). "As a result, the ER+ cancer sample was clustered with ER+ tumor cells (ESR1+, KRT18+, and KRT5−), KRT5+/EPCAM+ double-positive cells, cancer-associated fibroblasts (CAFs) (DCN+), macrophages (CD68+), KRT5+/EPCAM− cells, and endothelial cells (VWF+)." (PMID 34685653, 2021). "In the present study, immunoaffinity magnetic beads combined with an antiepithelial cell adhesion molecule (EpCAM) antibody were used to isolate tumor-derived EVs from plasma samples." (PMID 34439276, 2021). "This device exploits antibody-coated magnetic particles targeting EpCAM to detect and quantify circulating tumor cells (CTCs) of epithelial origin in the whole blood of patients with metastatic breast cancer, prostate cancer, and colorectal cancer." (PMID 34885161, 2021). "Many CTC assays, including CellSearch, rely on EpCAM enrichment for identification of tumor derived cells." (PMID 33801459, 2021). "EpCAM, a well-known biomarker of circulating tumor cells and cancer stem cells, has been actively investigated as a therapeutic target using mAbs in primary or adjuvant settings; however, this has displayed limited clinical efficacy." (PMID 34439094, 2021). "For example, circRNAs of the oncogene EPCAM were only expressed in tumor tissues, whereas the expression of relevant mRNAs exhibited a 25-fold increase." (PMID 34857007, 2021). "EpCAM can be downregulated during epithelial-to-mesenchymal transition, which can precede transmigration of tumor cells from interstitial tissues to the intravascular space, limiting CTC detection." (PMID 33614766, 2021). "Both epithelial- and mesenchymal-associated genes were commonly expressed at higher levels in CTCs compared to the bulk primary tumour, although some common EMT-associated genes (CDH1, VIM, EGFR, EPCAM) remained unchanged." (PMID 34206049, 2021). "Briefly, it has been earlier demonstrated that the frequency of tumor-initiating cells is ten times higher in the EpCAM+ fraction of breast CSCs than in the EpCAM− fraction." (PMID 34073849, 2021). "In some epithelial cancers, EpCAM expression varies within tumor subtypes and representative examples are discussed here." (PMID 34209658, 2021). "Epithelial cell adhesion molecule (EpCAM) is specifically expressed on the surface of epithelial cells and epithelial‐derived tumor cells." (PMID 33675149, 2021). "As a specificity test we selected the epithelial cell adhesion molecule (EpCAM) since it is a reference marker in circulating cancer cell capture approaches and is used to search for disseminated tumor cells in bone marrow biopsies." (PMID 34155195, 2021). "Our results indicate a high discrepancy (>60%) in the ESR1/PR status between the primary tumor and EpCAM(+) CTCs, and that ER/PR are expressed at a very low percentage in CTCs in respect to paired primary tumors." (PMID 33799422, 2021). "EnAd-EPCAM BiTE expresses a CD3/EPCAM BiTE which activates human T cells to kill tumor cells in vitro and from ex vivo patient ascites." (PMID 34445759, 2021). "EpCAM acts by the activation of Wnt signaling and increasing the c-Myc expression in highly proliferating tumor cells." (PMID 35070966, 2021).
tumor (continued). "Analogically, in nasopharyngeal carcinoma, tumor cell xenografts of the HK1 cell line with high expressions of CD44 and EpCAM showed a more rapid growth than the ones where tumor cells’ expression of CD44 was diminished." (PMID 33540535, 2021). "Taken together, these results highlight the association between proximal tumor-gained promoters with EZH2 and SUZ12 occupancies, which potentially affects the expressions of developmental regulatory genes such as EPCAM." (PMID 33916417, 2021). "CAR T cells designed with anti-Her2 DARPin or DARPins specific for Her2, epidermal growth factor receptor (EGFR), and epithelial cell adhesion molecule (EpCAM) showed potent tumor regression in preclinical models." (PMID 34209505, 2021). "The combination of EpAb2–6 (anti-EpCAM monoclonal antibody) with atezolizumab (anti-PD-L1 antibody) has been shown to almost completely eliminate tumours in an orthotopic model of human colorectal cancer." (PMID 33789677, 2021). "Using automated digital images-based evaluation of EpCAM-stained tumor specimens, we correctly analyzed all tumor fragments of the pilot cohort and 91% of tumor fragments in the validation cohort." (PMID 34834440, 2021). "Despite this compelling evidence supporting the tumor-promoting role of EpCAM, its anti-tumorigenic effects have also been noted." (PMID 34453639, 2021). "Our experience with CTC for the monitoring of tumor growth in this head and neck model shows an increased sensitivity when utilizing TxViva as a detection method in comparison to EpCAM only capture method." (PMID 34600526, 2021). "CD3/CD28 Dynabeads and an EpCAM BiTE, which targets EpCAM on tumor cells and CD3ε on T cells, were included as positive controls for activation-induced cell death (AICD) and BiTE-induced T cell death." (PMID 33820820, 2021). "Following virus inoculation in cultivation media, viral infection and BiTE expression were detected in malignant tissue containing EpCAM-positive tumor cells and FAP-expressing CAFs via immunohistochemistry (IHC) and fluorescence microscopy." (PMID 33863363, 2021). "In this study, we investigated the specific delivery of designed ankyrin repeat proteins (DARPins) directed against human epidermal growth factor receptor 2 (HER2) or epithelial cell adhesion molecule (EpCAM) in complex 3D tumor microenvironments." (PMID 34070171, 2021). "To address this further, we used flow cytometry to investigate the expression of these checkpoint molecules in tumor epithelium (EpCAM)_compared with mesenchymal cell susbets and vasculature (CD31) in a smaller cohort of patients (n = 12)." (PMID 34740105, 2021). "Compared with untargeted micelles that showed passive tumor targeting capability only, anti-EpCAM-conjugated micelles had active and passive targeting capabilities, resulting in a higher tumor aggregation rate of micelles in tumors even after 48 h." (PMID 34051801, 2021). "In fact, EpCAM is widely used as a marker for the detection or the isolation of circulating tumor cells derived from ovarian, breast, or colorectal cancers." (PMID 33850145, 2021). "Because we used U6 to quantitatively normalize miRNA levels, we were able to calculate the relative expression of miRNAs in EpCAM-positive EVs from the plasma of the tumor group and the healthy group." (PMID 34439276, 2021). "In this array, KCNJ8 showed a higher expression in CAFs (FAP+) compared to tumor epithelial (EpCAM+) cells." (PMID 33802791, 2021). "Aside from affecting intercellular adhesion, EPCAM influences other important functions relevant to tumor progression including cell proliferation and cancer stemness, which suggests an active role of EPCAM in cancer metastasis." (PMID 33916417, 2021). "Many cancer types lose EpCAM expression during tumor cell dissemination with EMT and/or dedifferentiation." (PMID 34209658, 2021).
tumor (continued). "PLA was performed using unconjugated anti-CXCR4 and anti-CCR7 antibodies, together with an Alexa Fluor® 488 anti-EpCAM antibody to distinguish epithelial tumour areas from tumour stroma for subsequent quantitation." (PMID 34685420, 2021). "For example, CD44 12-14, CD133 15, and EpCAM 16 were often used as markers of traditional tumor stem cells." (PMID 34239355, 2021). "We then used recombinant human EpCAM to competitively block binding of the goat polyclonal R&D EpCAM antibody on feline tumor cell lines." (PMID 33614766, 2021). "In our study, the expression of three markers (CK7, EpCAM, N-cadherin) was evaluated in the primary tumor." (PMID 33801519, 2021). "These HCC subtypes showed distinct tumor phenotypes: EpCAM‐positive (EpCAM+) HCC was characterized by a high tumor growth, invasiveness, and chemoresistance to cytotoxic agents, while CD90‐positive (CD90+) HCC was characterized by high metastatic potential." (PMID 33834612, 2021). "In 10 out of the 16 intraoperative blood samples (Reservoir, EC) (63%), EpCAM-positive tumor cells were detected in the different Catuvab procedure steps." (PMID 34715784, 2021). "In the three CAF isolates from HCC derived from patient 1–3 cancer stem cells (CSC) positive for CD13, CD44, CD90, CD133, OV6, epithelial cells or CSCs positive for EpCAM, or general tumor cells positive AFP were identified by immunofluorescence." (PMID 34947582, 2021). "As a representative tissue, we focused on solid tumors of the breast overexpressing the tumor marker epithelial cell adhesion molecule (EpCAM), while in some instances, we used normal skeletal muscle tissue for comparison." (PMID 33921165, 2021). "Expression of EpCAM was significantly increased in metastatic samples compared with primary tumor tissues in COAD and READ." (PMID 34790117, 2021). "Taken together, a co-stimulatory αCD28 BiMAb engaging the highly expressed antigen EpCAM enhanced the efficacy of αCD3 BiMAb recognizing a second TAA on the same tumor cell." (PMID 34484225, 2021). "We then assessed αV protein expression in 18 additional freshly resected tumours using specific mAb, combined with anti-EpCAM and anti-E-cadherin to delineate integrin expression on epithelial cancer cells." (PMID 34471106, 2021). "In esophageal cancer patients, EpCAM expression was lower in lymph node and bone marrow disseminated tumor cells (DTCs)." (PMID 34209658, 2021). "Subsequently, the EpCAM antibody (anti-EpCAM) was modified on the surface of AuNPs to enhance the specificity of EpCAM-positive tumor cells." (PMID 34858966, 2021). "Two tumor-associated proteins MUC1 and EpCAM exhibit a highly positive correlation, thereby suggesting a consistent role in cancer metastatic progression." (PMID 34099708, 2021). "A higher avidity cross-reactive or feline-specific antibody will be required to further investigate EpCAM expression in normal and neoplastic feline tissue or for detecting CTCs in the blood of tumor-bearing cats." (PMID 33614766, 2021). "Amongst the human tumour compartment markers, EpCAM and E-Cadherin showed a strong positive correlation (ρ = 0.57) and together with CD24, marked human luminal epithelial tumour cells." (PMID 33790302, 2021). "For EnAd-SA-EpCAMBiTE, transgene expression to was restricted to EpCAM-positive tumor cells in contrast to EnAd-CMV-EpCAMBiTE, which induced BiTE expression also in macrophages and other cells present in the malignant fluids." (PMID 33863363, 2021). "First, tumor cells were detected by flow cytometry of bone marrow from the tibiae and femora from Hif1αf/f PyMT+ and Hif1α−/− PyMT+ mice based on epithelial cell adhesion molecule (EpCAM) positivity." (PMID 34556788, 2021). "EPCAM, a commonly employed epithelial-associated gene in the CTC field, had CTC expression levels similar to primary tumours." (PMID 34206049, 2021).
tumor (continued). "EpCAM is also frequently the target of methods to capture and measure circulating tumor cells (CTCs) in epithelial cancer patients, which provides important prognostic information and can help to determine the response to therapeutic interventions." (PMID 34209658, 2021). "The authors reasoned that EpCAM expression was silenced during the early stages of tumor cell dissemination and metastasis formation, and that this was related to EMT." (PMID 34209658, 2021). "EPCAM mRNA levels were lower in the tumour tissue than non-tumour and the IHC label was also lower in tumour relative to non-tumour however both tumour and non-tumour were categorised as 1–25% stained and not sufficiently different to be distinguishable." (PMID 33906633, 2021). "The proportion of the EpCAM–CK7+N-cadherin– tumor cells was significantly higher among CTCs compared to the primary tumor; on the contrary, the percentage of EpCAM+CK7+N-cadherin+ cells was higher in the primary tumor." (PMID 33801519, 2021). "Univariate analysis confirmed the prognostic value of combined gene expression of CK-19, and/or CD44high/CD24low, and/or ALDH1high/CD24low and/or HER2 in the EpCAM(+) CTC fraction for OS (p = 0.001) together with tumor grade (p = 0.030) and ER (p = 0.004)." (PMID 33799422, 2021). "The conjugation of anti-EpCAM promoted the selective accumulation of HNTs-FITC-ICG-RBCM-SA-EpCAM in the tumor region." (PMID 34361636, 2021). "Primary carcinomas, metastases, and cancer stem cells express high levels of EpCAM too, whereas circulating and disseminated tumor cells (CTCs/DTCs) display heterogeneous EpCAM expression with frequent loss during EMT." (PMID 34693227, 2021). "EpCAM and EpICD can also regulate and/or be controlled by reprogramming factors involved in promoting tumor initiating cells (TICs), also known has cancer stem cells (CSC)." (PMID 34209658, 2021). "We stained tissues from endpoint tumors from OT1+Mrb-OVA-treated mice with antibodies for mouse CXCL16 and EpCAM (tumor cell marker) and CD45 (immune cells)." (PMID 34607898, 2021). "For example, the oncogene EPCAM, which had two novel circular isoforms, was only expressed in tumor tissues and is known to contribute to the formation of the protein epithelial cellular adhesion molecule (EpCAM)." (PMID 34857007, 2021). "In our study, expression of three markers (CK7, EpCAM, N-cadherin) was evaluated in the primary tumor." (PMID 33801519, 2021). "By using a such system, which captures tumor cells from whole blood based on EpCAM and cytokeratin expression, a PDA diagnosis was made in 32 % of patients in a cohort consisting of advanced PDA and 7 % in a cohort consisting of early stage PDA." (PMID 33593396, 2021). "Nearly all cells of 2DO expressed epithelial cell adhesion molecule (EpCAM) like epithelial-derived tumor cells." (PMID 33990627, 2021). "Other studies used tumor-associated antigens such as EGFR and EpCAM that are present on vital healthy tissues, leading to toxicities if targeted systemically." (PMID 33863363, 2021). "An intense EpCAM overexpression is observed in 40–60% of collected tumor samples, and a reliable stratification method is thus required for a successful clinical application of the targeted therapies." (PMID 34298801, 2021). "With these exciting properties, iFMNS allows convenient and simultaneous tumor cell fluorescent immuno-labeling and magnetic isolation via the specific targeting to EpCAM." (PMID 33892737, 2021). "Our results based on this prospective liquid biopsy study using identical blood draws clearly indicate a significantly higher positivity of gene expression and tumor DNA methylation markers in EpCAM-positive CTCs compared to plasma-derived exosomes." (PMID 33668490, 2021). "Catumaxomab, which binds EpCAM on tumor cells and CD3 on T cells while retaining affinity to FcγR-positive cells, was the first clinically successful T-BsAb and was approved as a therapeutic agent for malignant ascites by the European Union in 2009." (PMID 34832954, 2021).